EPCAM (epithelial cell adhesion molecule)
Diseases named in the same sentence as EPCAM in open-access papers (continued):
Sharing a sentence is not in itself a finding about the gene and the disease.
breast carcinoma (continued). "Collectively, these results suggest that deglycosylated EpCAM regulated autophagy in breast cancer cells." (PMID 34983878, 2022). "Annexin A2 (ANXA2) was found to be selectively and differentially co‐immunoprecipitated with EpCAM in the ERα+ breast cancer cells MCF‐7 and ZR‐75‐1." (PMID 34240826, 2022). "As a negative control, MDA‐MB‐231 and Hs578T were used since they express a negligible amount of EpCAM and are known as EpCAM−/low ERα−/low invasive and tumorigenic breast cancer cell lines." (PMID 34240826, 2022). "This technique utilizes label-free nanotube-antibody microarrays using breast cancer-specific antibodies, such as anti-EpCAM and anti-HER2." (PMID 35565189, 2022). "In this study, we investigated the antitumor effect of a defucosylated anti-EpCAM mAb (EpMab-37-mG2a-f) against a breast cancer cell line, BT-474 derived from luminal B HER2-positive subtype." (PMID 36546899, 2022). "Polymeric NPs coated with hRBCm constitute a novel biomimetic nanocarrier with a Na131I cargo, and an anti-EpCAM targeting nanotheranostic for breast cancer was developed." (PMID 35877345, 2022). "In vitro assessments showed higher cellular toxicity and cellular internalization of Apt-Pep@MUA.GNR-DOX in EpCAM overexpressing breast cancer cell lines (4T1 and MCF-7) in comparison with that of Pep@MUA.GNR-DOX." (PMID 36045404, 2022). "The engineered CAR‐T cells displayed strong and specific cell‐killing actions against EpCAM‐expressing breast carcinoma cells, resistant to the natural cytotoxicity produced by unmodified NK cells." (PMID 35762299, 2022). "The EpCAM+ breast cancer epithelial cells were respectively isolated from PyMT and PyMT;Zeb1cKO mice to perform RNA sequencing." (PMID 35246504, 2022). "A phase I study for hormone refractory prostate cancer patients and a phase IB study for EpCAM-positive relapsed or refractory advanced-stage breast cancer confirmed the feasibility of adecatumumab." (PMID 36369033, 2022). "The MCF 7 breast cancer cell line overexpresses a membrane antigen called the epithelial cell adhesion molecule, EpCAM." (PMID 36551029, 2022). "Epithelial cell adhesion molecule (EpCAM) is also another transmembrane glycoprotein, which is overexpressed in cancerous epithelial cells with fast proliferation and can be found in breast cancer cells." (PMID 35743245, 2022). "The assessment of the protein levels of ANXA2 and EpCAM relative to GAPDH showed that ANXA2 is expressed in all breast cancer cell lines whilst EpCAM is expressed only in the ERα+ cells ZR‐75‐1 and MCF‐7." (PMID 34240826, 2022). "Taken above, these data indicate that deglycosylated EpCAM-induced autophagy participated in the proliferation an apoptosis viaI3K/Akt/mTOR signaling in breast cancer cells." (PMID 34983878, 2022). "According to such additional filter, six cancer-specific proteins in colon cancer (CEACAM8, CDH17, GLOD5, PPM1E, TRIM16, EPCAM) and one in breast cancer (CCR9) were identified." (PMID 36243758, 2022). "Through our study, we illustrated that autophagy and subsequent apoptosis were induced by deglycosylated EpCAM in breast cancer cells." (PMID 34983878, 2022). "To understand the mechanism of deglycosylated EpCAM-mediated autophagy in breast cancer cells, we analyzed the Akt-mTOR signaling pathway." (PMID 34983878, 2022). "Our study further explore EpCAM functions and provides a theoretical basis for the treatment of breast cancer." (PMID 34983878, 2022). "EpCAM expression in breast cancer was previously analyzed and showed varied clinical outcomes in the intrinsic subtypes." (PMID 36546899, 2022). "EP-CAM can strengthen the tumor-initiating ability by influencing EMT, which is induced through N-glycosylation of EpCAM in breast cancer." (PMID 36107005, 2022). "A DNA computation device mediated by thermophoresis efficiently differentiated HER2 ± EpCAM + breast cancer (BC) patients from healthy donors and distinguished HER2 + BC patients from HER2- BC patients." (PMID 36167539, 2022).
breast carcinoma (continued). "EpCAM expression has also been shown to be upregulated in a variety of carcinomas, such as breast cancer." (PMID 35664698, 2022). "The proportion of CD63/EpCAM/mucin-1 vesicle in patients with breast cancer was significantly higher than that of healthy control with overall accuracy of 91%." (PMID 35565189, 2022). "Blockade of autophagy with autophagy inhibitor Wortmannin completely inhibited deglycosylated EpCAM-induced autophagy apoptosis in breast cancer cells." (PMID 34983878, 2022). "EpCAM knockdown promoted apoptosis and raised the cytotoxic effect of 5-Fluorouracil in breast cancer cells through MAPK signaling pathway." (PMID 34983878, 2022). "As we did for cells, we checked the purity of our endothelial EV preparations by assessing the level of the endothelial marker CD31 and the breast cancer marker EpCAM." (PMID 35656866, 2022). "In conclusion, the combination of autophagy modulation and EpCAM targeted therapy is a promising therapeutic strategy in the treatment of breast cancer." (PMID 34983878, 2022). "A phase 1 trial (NCT02915445) conducted on patients with NPC or breast cancer aimed to evaluate the therapy with CAR-T cells specifically targeting epithelial cell adhesion molecule (EpCAM)." (PMID 36713430, 2022). "We validated various expression levels of HER2 in four EpCAM-overexpressed breast cancer cell lines by flow cytometry (FCM) and Western blot analysis, the strongest in SK-BR-3, moderate in MDA-MB-453, low in MCF-7, and negative in MDA-MB-468 cells." (PMID 36246381, 2022). "Quantitative analysis of EpCAM and other biomarkers on exosomes has shown prospects in blood sample identification of pancreatic and breast cancer." (PMID 36369033, 2022). "In breast cancer cell lines, downregulation of EpCAM reduces proliferation, migration, and invasion." (PMID 36428553, 2022). "The patient with breast cancer, in particular, was positive for hormone receptors and had 3700 CTCs as assessed by immunostaining for cytokeratins upon EpCAM-based immunomagnetic capture." (PMID 36428760, 2022). "This study presents a novel finding that ANXA2 is an interacting partner of EpCAM in the EpCAM+ ERα+ breast cancer cells, and co‐localizes with EpCAM at the plasma membrane of EpCAM+ ERα+ breast cancer cells." (PMID 34240826, 2022). "We reported that deglycosylated EpCAM induced autophagy and apoptosis in breast cancer cells in this study." (PMID 34983878, 2022). "The epithelial cell adhesion molecule (EpCAM) is a type I transmembrane and glycosylated protein which is overexpressed in many neoplasms including high grade glial tumors, breast cancer, and colorectal cancer." (PMID 34240826, 2022). "Taken together, we deduced that deglycosylated EpCAM promote autophagy via PI3K/AKT/mTOR signaling pathway in breast cancer cells." (PMID 34983878, 2022). "Another example includes halloysite nanotubes loaded with ICG which were coated with antibody-modified RBC membranes to target epithelial cell adhesion molecule (EpCAM) receptors that are overexpressed on breast cancer cells." (PMID 35960404, 2022). "Deglycosylated EpCAM was found to be a functional marker that was required for AKT/mTOR mediated autophagy regulation in breast cancer cells." (PMID 34983878, 2022). "In breast cancer, it has been shown that expression of IL-8 can be modulated by the manipulation of EpCAM expression in vitro." (PMID 35155394, 2022). "The efficiency for capture of breast cancer cells (MDA‐MB‐468) with high expression of EpCAM was greater than 93%." (PMID 37324582, 2022). "The PLGA nanoparticle was coated in human red blood cell membranes and labeled with epithelial cell adhesion molecule (EpCAM) antibody to enable it to target EpCAM overexpression by breast-cancer cells." (PMID 35877345, 2022).
breast carcinoma (continued). "The correlation between the stage and grade of breast cancer and overexpression of EpCAM in the tumour tissue was observed." (PMID 35208477, 2022). "NIS plays a crucial role in enhancing Na131I delivery, and was utilized in conjunction with anti-EpCAM to target breast-cancer cells specifically." (PMID 35877345, 2022). "Flow cytometry fluorescence imaging visually signified delivery by EINPs specifically to breast-cancer cells as a result of anti-EpCAM targeting." (PMID 35877345, 2022). "The limitation of EpCAM-dependent CTC detection seems to be particularly pronounced in early stage breast cancer." (PMID 36428760, 2022). "EpCAM-dependent isolation methods, such as the CellSearch® system, predominate in breast cancer CTC clinical studies." (PMID 36428760, 2022). "We also found that deglycosylated EpCAM promoted apoptosis and inhibited proliferation through activating autophagy by suppressing Akt/mTOR signaling pathway in breast cancer cells." (PMID 34983878, 2022). "Six individuals with breast cancer and three healthy control individuals were recruited for this study, which evaluated EpCAM-positive exosomes in the plasma samples." (PMID 35664698, 2022). "For example, adecatumumab targeting EpCAM inhibited breast cancer metastasis in a dose and target-dependent manner, thus catumaxomab targeting EpCAM has already been approved for the treatment of cancers." (PMID 35414783, 2022). "A live/dead cell assay was performed to determine the MCF-7 cellular binding/uptake of EINPs to verify that the EINPs anti-EpCAM functionalized nanotheranostic carriers accurately targeted the MCF-7 breast-cancer cells." (PMID 35877345, 2022). "Primary breast cancer cells (EpCAM+/CD45−) and TAMs (EpCAM−/CD45+/F4/80+/CD206+) were isolated and cultured in suspension separately for 48 h modified from a previous report." (PMID 35680853, 2022). "For EpCAM-dependent breast cancer invasion, the transcription factor AP-1 was reported to participate in the MEKK1/MKK7/JNK pathway, while EpCAM was shown to modulate the effects of NF-κB and IL-8 during BC progression." (PMID 36369033, 2022). "Activation of the AKT pathway is also observed in EpCAM overexpressing ZR-75-1 breast cancer cell line, compared with parental cell line." (PMID 35392236, 2022). "EpCAM is frequently overexpressed in ductal and metastatic breast cancers and high EpCAM expression can serve as a poor prognostic marker." (PMID 34209658, 2021). "More recently, a clinical trial with CAR-T cells involving both NPC and breast cancer patients with epithelial cell adhesion molecule (EpCAM) CAR-T has been initiated." (PMID 36046116, 2021). "The plakoglobin (JUP), KRT8, KRT18, KRT19, CLDN4, and EPCAM, which their role in breast cancer metastasis was demonstrated in previous studies, are EMT markers." (PMID 34801010, 2021). "Clinical trials evaluating the EpCAM-targeting mAb adecatumumab for breast cancer treatment showed that the probability of tumor progression was significantly lower in patients with tumors expressing high levels of EpCAM and receiving a high dose." (PMID 34439094, 2021). "The epithelial cell adhesion molecule content on human breast cancer cell MCF-7 exosomes is high, so epcam aptamers and cholesterol-modified DNA can be selected for exosome identification and enrichment when detecting exosomes." (PMID 35087806, 2021). "Binding of the goat polyclonal R&D EpCAM antibody to the highest expressing feline oropharyngeal squamous cell carcinoma and human MCF-7 breast carcinoma cell lines was competitively inhibited by addition of recombinant human EpCAM." (PMID 33614766, 2021). "EpCAM overexpression in breast cancer correlates with tumor mass, lymph node status, and the presence of estrogen receptors." (PMID 34590615, 2021). "A statistically significant increase (p < 0.01) in EpCAM-positive exosomes was captured for breast cancer patients (n = 10), when compared to healthy individuals (n = 10)." (PMID 34073560, 2021).
breast carcinoma (continued). "In EpCAM-positive breast cancer cell lines, NK92 cells expressing EpCAM-directed CAR and IL-15 presented selective and superior cytotoxicity than unmodified NK92 cells." (PMID 34072732, 2021). "EpCAM has also been shown to modulate IL-8 and NF-κβ expression and invasion in breast cancer cell lines." (PMID 34209658, 2021). "The monoclonal SB EpCAM antibody yielded more consistent adhesion than the polyclonal R&D EpCAM with the high EpCAM-expressing MCF-7 human breast carcinoma cell line, further illustrating that the latter antibody would not be optimal for CTC detection." (PMID 33614766, 2021). "In another study, the microfluidic platform with biosensing applications using gold surface and epithelial cell adhesion molecule (EpCAM) antibody (Ab) was used for the detection of human breast cancer cell line (MCF-7)." (PMID 33808043, 2021). "EpCAM has been found to be a particularly potent biomarker for breast cancer metastisis, known to be one of the most important factors in patient mortality." (PMID 34439139, 2021). "Aptamers designed to bind several targets including nucleolin or EPCAM, overexpressed in breast cancer, or aptamers selected to bind to breast cancer 4T1 cells, are also of relevance." (PMID 34884816, 2021). "We used the MDA-MB-468 breast cancer cell line, which expresses moderate amounts of both EpCAM and CTSL." (PMID 33980181, 2021). "Lastly, we selectively captured breast cancer cell EVs spiked in blood plasma using anti‐EpCAM antibody on the FO‐SPR surface." (PMID 33664936, 2021). "CellSearch is the only clinically validated method of detecting EpCAM in metastatic breast cancer patients and works by conjugating EpCAM-specific antibodies with ferrofluid, allowing for magnetic separation." (PMID 34439139, 2021). "There is a higher frequency of EpCAM expression in metastatic vs. primary tumors and ductular compared to lobular carcinomas in human breast cancer patients." (PMID 33614766, 2021). "Co-expression of HER2 and EpCAM correlates with a poor prognosis, e.g., in breast cancer, which additionally supports the development of co-targeted therapies for these patients." (PMID 34439094, 2021). "Compared to healthy controls, plasma levels of epithelial cell adhesion molecule (EpCAM) -positive exosomes have been found to be significantly higher in breast cancer patients." (PMID 34234872, 2021). "Lobular and other histological breast cancer subtypes, however, usually have lower EpCAM expression." (PMID 34209658, 2021). "Here, we report the engineering and testing of BiMAb and bifunctional TNFL fusion proteins targeting various well-established breast cancer-associated TAAs, including EGFR, HER2, CEA, EpCAM, and the tumor stroma antigen FAP." (PMID 34484225, 2021). "We found that the unaffected normal mammary epithelium in the section of the grade III mammary tubular carcinoma had positive membranous staining with the R&D EpCAM antibody, but variable expression was seen within the mammary carcinoma in the same section." (PMID 33614766, 2021). "EV-mediated reduction in drug availability has also been observed in epithelial cell adhesion molecule (EpCam)-positive breast cancer cells treated with the EpCam-specific antibody C215, suggesting a correlation between EV release and tumor progression." (PMID 33670185, 2021). "EMT in breast cancer is also affected by the N-glycosylation of EpCAM via multiple cell signaling pathways." (PMID 33889547, 2021). "The HNTs-FITC-ICG-RBCM nanocarrier was further linked with anti-EpCAM to endow it with targeting therapy performance against breast cancer, and the anti-EpCAM-conjugated nanocarrier exhibited significantly tumor-specific accumulation." (PMID 34361636, 2021). "Epithelial derived cell adhesion molecule (EpCAM) biomarkers (CA 15–3, CA 27.29) from breast cancer are also detected by a microfluidic system from blood by using immunomagnetic separation method." (PMID 33417986, 2021).
breast carcinoma (continued). "In breast cancer cell lines with an epithelial phenotype, EpCAM promoted invasion, while in cell lines with a mesenchymal phenotype, EpCAM had minimal impact on invasion." (PMID 34209658, 2021). "This is in agreement with Zhang and colleagues who established long-term culture from CTCs ALDH1A1(+); EpCAM(−) in breast cancer suggesting that this CTC population was able to form brain metastasis." (PMID 34071445, 2021). "Our results indicate that EpCAM is expressed in specific epithelia in cats but is variably expressed in feline mammary tumors and oropharyngeal squamous cell carcinoma." (PMID 33614766, 2021). "For surface detection of EpCAM, we used flow cytometric analysis on cell lines derived from normal mammary and renal epithelium, mammary tumors and oropharyngeal squamous cell carcinoma." (PMID 33614766, 2021). "Western blot analysis show that EpCAM-positive breast cancer exosomes express AnxA2 and exosomal markers CD9, TSG101, and flotillin-1." (PMID 31992335, 2020). "The EpCAM-independent integrated subtraction enrichment and immunostaining-FISH (SE-iFISH) method was used to investigate the role of EpCAM expression on CTCs and disseminated tumor cells (DTCs) in patients with breast cancer." (PMID 32764280, 2020). "The overexpression of these mRNAs (EpCAM,BIRC5 andYBXI) were all associated with poor outcomes for breast cancer patients." (PMID 33447385, 2020). "CD44+ CD24−/low ESA+ (epithelial surface antigen, also known as EpCAM) cells were identified as CSCs in a number of solid malignancies such as breast cancer." (PMID 32684928, 2020). "Compared to the expression of PAI1, a gene known to correlate with worse outcome in patients, or EPCAM, a gene that is commonly overexpressed in breast cancer, breast CTCs expressed low levels of PISD." (PMID 32503622, 2020). "To demonstrate the ability of TEPP-DOX to target EpCAM-positive, metastatic, breast cancer brain metastases, we made use of the brain-metastatic variant of MDA-MB-231 (MDA-MB-231Br)." (PMID 32027209, 2020). "Using anti-EpCAM-FITC in analogy to the standardised maintrac method we have determined CETCs in the blood of breast cancer patients." (PMID 32104205, 2020). "As a proof of concept, we demonstrated the feasibility of capturing breast cancer cell lines from solution through EpCAM functionalized hydrogel microparticles synthesized using our DML technique." (PMID 31973077, 2020). "EpCAM+/CD44+ CTCs isolated from breast cancer patients inflicted bone metastasis in immunodeficient NSG mice." (PMID 33207810, 2020). "This was confirmed by measuring the expression levels of three different surface markers, HER2, EGFR, and EpCAM, expressed on breast cancer cells, by immunofluorescence analysis." (PMID 33659239, 2020). "A capture yield of more than 95% of the MCF-7 cell line (an EpCAM-positive breast cancer cell line) from artificial blood samples was achieved at an optimal flow rate of 1.0 mL h−1." (PMID 32823926, 2020). "Exosomes isolated from pleural effusions from breast cancer patients have increased levels of the epithelial marker proteins EpCAM and CD24 compared to controls." (PMID 33322643, 2020). "The expression of NICD and Hes1 was also reduced in EpCAM+ breast cancer cells from PyMT;Zeb1cKO mice compared with that from PyMT mice." (PMID 33046710, 2020). "The functionalized anti‐EpCAM antibody (QD‐EpCAM) was modified at the 3D biomimetic interface to successfully achieve the highly specific detection of MCF7 breast cancer cells as a CTC model." (PMID 32101379, 2020). "Yu and colleagues proved that EMT exists in human breast cancer specimens, and they used three antibodies (EGFR, HER2 and EpCAM) to capture breast cancer cells more efficiently." (PMID 32823926, 2020). "In the specialized Human EpiCult-C environment, the increase in EpCam+ breast tumor cells of breast cancer patient St23784/17 differed from the culture of EpCam+ cells of patient Ti41749/17." (PMID 32523653, 2020).